GZMB (granzyme B)
Diseases named in the same sentence as GZMB in open-access papers (continued):
Sharing a sentence is not in itself a finding about the gene and the disease.
cancer (continued). "Granzyme B (GranB) is a main component of the cytotoxic activity of CD8+ T cells and natural killer (NK) cells during the cellular immune response against cancer cells." (PMID 31766292, 2019). "Other controls including supernatants from (a) cancer cells alone and (b) Jurkat T cells, as well as (c) media alone, showed undetectable amounts of released IFN-γ and granzyme B by ELISA." (PMID 31514488, 2019). "Among the genes that we found down-regulated are: GZMA, GZMB, HLA-A, -B, -C and IFNG, all supporting a model of impaired CD8 T cell cytotoxic activities, one of the most important anti-cancer responses." (PMID 29928478, 2018). "The nuclear FGFR1 arises from the proteolytic processing of the full-length receptor by granzyme B. Importantly, the synthetic peptide inhibitor specific towards granzyme B blocked FGFR1 processing, nuclear translocation, and the migration of cancer cells." (PMID 30577533, 2018). "The toxicity was attributed to GzmB-mediated apoptosis, indicating the potential use of HA–EGCG as effective intracellular protein carriers for targeted cancer therapy." (PMID 28181831, 2017). "In some cancers, such as gastric, colon, and lung cancers, MAIT cells can migrate from the peripheral blood to affected tissues, express GzmB and perforin, and thus have the potential to kill cancer cells in patients with mucosal-associated cancers." (PMID 29176983, 2017). "The cytolytic molecules, such as granzymeA, granzyme B, perforin, and granulysin from γδ-T exosomes,induced specific apoptosis of cancer cells without harming normalcells." (PMID 39862206, 2025). "GZMB can inhibit the T cell proliferation, PTPRS can inhibit the production of interferon, and CLIC3 takes part in the angiogenesis and increases the invasiveness of cancer cells." (PMID 40755770, 2025). "Without perforin, NK cells are unable to perform granzyme B–mediated serial killing and only kill via death receptors, which significantly prolongs the time required to kill cancer cells." (PMID 40163355, 2025). "In addition, TBX3 overexpression inhibited GZMB expression on CD8+ T cells, suggesting that TBX3 reduces the cancer-killing efficiency of CD8+ T cells." (PMID 39897553, 2025). "Granzyme B is a serine-protease released by CD8+ T cells and natural killer cells during the cellular immune response and represents one of the two dominant mechanisms by which cytotoxic T cells mediate cancer cell death." (PMID 40395227, 2025). "Interestingly, CD4+ Texterm phenotype exhibited the highest expression of cytotoxic markers (PRF1, GZMA, GZMB, IFNG, and GNLY), aligning with recent discoveries indicating that cytotoxic CD4+ T cells within tumors can directly kill cancer cells." (PMID 40335494, 2025). "In cytotoxic T cells/NK cells, we found that SUDV-induced IL-6 was predicted to induce SOCS3 expression and the downstream suppression of STAT5, granzyme B (GZMB) and PRF1 expression, leading to suppressed apoptosis of APCs and cancer cells, as well as pore formation." (PMID 41181097, 2025). "For example, some cancer cells increase the expression of inhibitors, such as SERPINB9, which protect them from GZMB-induced apoptosis, allowing to survive despite the presence of GZMB-secreting immune cells." (PMID 40766321, 2025). "Interestingly, when TGFβ1 was blocked with a TGFβ1-neutralizing antibody, the cancer-killing efficiency of CD8+ T cells significantly increased, along with an increased proportion of IFN-γ+ and GZMB+ CD8+ T cells." (PMID 39897553, 2025). "Additionally, we collected the IC50 values of drugs from various cancers and cell lines from the GDSC and CTRP databases in order to correlate them with GZMA, GZMB, GZMK and PRF1 expression levels." (PMID 40002821, 2025).
cancer (continued). "Consistently, analysis of the LUSC cohort profiled by the TCGA also revealed that OTUB2 was more highly expressed in cancer tissues than in normal tissues, while the CTL signature genes CD8A and GZMB were expressed at significantly lower levels in cancer tissues than in normal tissues." (PMID 38167274, 2024). "Similarly, we observed that across multiple cancer types, OTUB2 expression was negatively correlated with the expression of the CTL signature genes GZMB, GZMA and CD69." (PMID 38167274, 2024). "Conclusively, Pereskia bleo leaves could potentially modulate the anti-cancer immune response by up-regulating IFN-γ, IL-12, IL-18, perforin, and granzyme B, while downregulating IL-8 and IL-10 in healthy blood samples." (PMID 39619199, 2024). "In this regard, there is a report on significantly decreased percentage of perforin‐expressing NK cells (but not granzyme B) in different types of cancers." (PMID 38652012, 2024). "Notably, CD34, IL7R, NRP1, GZMB, FGF7, and ENO2 exhibited significant expression in cancer stem cells, CD4+ memory cells, regulatory T cells, NK cells, fibroblasts, and neurons, respectively." (PMID 38846945, 2024). "In addition to GSDMD, HsGSDME has been reported to be cleaved by both CASP3 and granzyme B at the same 267DMPD270 site, leading to the enhanced cytotoxicity of GSDME on cancer cells." (PMID 37134086, 2023). "Importantly, they also released effector molecules (e.g. interferon-γ, granzyme B and perforin), mediated cytotoxicity against CD176+ cancer cells, and maintained functionality upon repetitive antigen stimulation." (PMID 37915564, 2023). "Interestingly, the findings suggested a correlation between HIF1AN in breast malignancy and PDCD1, LAG3, CTLA4, and GZMB of T cell exhaustion as well as chemokine ligand CCL2 of TAMs." (PMID 36816977, 2023). "Comparable to the results in immunodeficient human cancer CDXs, ANO1 knockdown reduced the growth of CT26 CDXs, paired with increased CD8/granzyme B and decreased PD‐L1 IHC staining in xenograft tumors, suggesting a higher infiltration of cytotoxic CD8+ T cells in TIME." (PMID 37341301, 2023). "Interestingly, the expression levels of the cytotoxic effectors PRF1, GNLY, GZMA, GZMB and GZMH in CD8+ Tex subclusters were even richer than those in CD8+ Teff subclusters, which implied that CD8+ Tex cells still tended to respond to cancer cells." (PMID 35562760, 2022). "The load of the cytotoxic effector molecule granzyme B was similar in CAR T-cells and IFN-CAR T-cells ruling out that lack of cytolytic granules caused decline in anti-cancer cell activities." (PMID 36497099, 2022). "GSDMB, GSDMC, GSDMD, GZMB, and GSDME displayed extensive CNV amplification across cancer types." (PMID 35620284, 2022). "Here, we confirmed that soluble VISTA on its own (in the absence of galectin-9) prevents release of granzyme B from cytotoxic T cells into target cancer cells." (PMID 35634346, 2022). "Under hypoxia, cancer cells express HIF-1α, which helps to increase adenosine accumulation, but NK cells have impaired killing ability and lowered expression of NKG2D and intracellular perforin and granzyme B." (PMID 35815945, 2022). "As additional controls, we confirmed that probe H5 was not cytotoxic and did not stain cancer cells in co-cultures where T cells were inactive or in co-cultures that had been pretreated with the reversible GzmB inhibitor Ac-IEPD-CHO." (PMID 35501326, 2022). "Cytotoxic immune cells such as natural killer cells and CD8+ T cells can also trigger cancer cell pyroptosis through lymphocyte-derived granzyme A (GZMA) or granzyme B (GZMB) but not caspases-mediated cleavage of the GSDM family proteins." (PMID 35432318, 2022).
cancer (continued). "This assay enables to interrogate single cell expression levels of multiple mRNA of interest such as CD4, Cd8α, IFNγ and GZMB and their spatial distribution and can be used to detect, quantitate and evaluate the frequency and function of CAR T cells and cancer cells in tissues." (PMID 34155235, 2021). "Based on expression of high levels of TNF-α, IFN-γ, and granzyme B, CD8+ TRM cell infiltration in various human cancers is correlated with favorable clinical outcomes, and CD8+ TRM cells have emerged as a predictive marker of survival in several human epithelial cancers." (PMID 34604029, 2021). "However, the direct activation of GSDME by granzyme B implies that CTLs and NK cells are capable of inducing pyroptosis in GSDME-expressing cancer cells even when apoptosis signaling pathways are impaired in the targets." (PMID 33406603, 2021). "The differentially expressed proteins were identified in the signaling pathways of granzyme B, sirtuins, eIF2, actin cytoskeleton, eNOS, acute phase response and calcium and were connected to the upstream regulators MYC, PI3K SMARCA4 and cancer-related chemical drugs." (PMID 33656060, 2021). "Unlike effector T cells and NK cells which express and secrete perforin and granzyme B synergistically to fight against cancer, pDCs can produce and utilize a bulk amount of granzyme B independent of perforin." (PMID 33868318, 2021). "Moreover, it has been reported that cytotoxicity of HTLs against cancer cells is mediated through the release of effector cytokines such as IFN-γ, perforin, and granzyme B." (PMID 31221178, 2019). "Moreover, the panel allows for the visualization of additional features which are essential for the study of cancer immunology such as tissue residency-like (e.g., CD103+ T cells) and activation phenotypes (granzyme B+ T cells)." (PMID 31736961, 2019). "In addition, deletion of Smad3 also enhanced the anticancer activities of NK cells by increasing the levels of granzyme B, interleukin (IL)-2 and IFN-γ locally within the cancer microenvironment and in the systemic circulation." (PMID 28262747, 2017). "Through the production of granzyme-B, TH9 cells trigger cancer cell death." (PMID 27832300, 2017). "Subsequent analysis of mouse cancer tissues through flow cytometry revealed that RNase1 knockdown in 4T1 cells increased the proportion of CD8+ T cells expressing effector cytokines, including granzyme B (GB) and IFN‐γ, and reduced expression of ICs such as Pd‐1 and Tim‐3 on CD8+ T cells in the TME." (PMID 39932384, 2025). "We corroborated in cSCC patient samples that the frequency of GzmB+ cells decreased and the frequencies of CD8+PD-1+, CD8+LAG-3+, CD8+TIM-3+ and CD8+TIGIT+ cells increased in mixed and mesenchymal patient cSCCs, which are those tumors enriched in hybrid E/M and mesenchymal cancer cells." (PMID 38914547, 2024). "We analyzed cancer tissue samples from 79 NSCLC patients using multiplex fluorescence (mIF) staining to visualize various SHP-2+ TAM subpopulations (CD68+SHP2+, CD68+CD86+, CD68 + 206+, CD68+ CD86+SHP2+, CD68+ CD206+SHP2+) and T cells (CD8+ Granzyme B +) of immune cells." (PMID 38799432, 2024). "Also, the expression of effector T cell activation markers (IL-2, GZMB, IFNG) in edT cells were significantly lower after co-culture with T cell-resistant (R) as compared to -sensitive (S) cancer cells, indicating decreased T cell effector functionality and thus impaired PDAC cell killing." (PMID 38654067, 2024). "The killing of cancer cells by CD8+ T cells and NK cells purified from the same mice was also markedly reduced, and the reduced granzyme activity was reflected in the slower turnover of model peptide substrates specific to granzyme A (GzmA) and granzyme B (GzmB)." (PMID 39021839, 2024). "The Granzyme-B/GSDME and Granzyme-A/GSDMB driven pyroptosis have also been discovered in natural killer cells and lymphocytes, which may further enhance the immune response to cancer." (PMID 39398428, 2024).
cancer (continued). "These CD4+ cytotoxic T cells (CTLs) display both lytic granule (via granzyme B (GzmB) and perforin) as well as Fas/FasL mediated cytotoxicity in an MHC class II-dependent manner, and develop especially in the context of prolonged antigen stimulation, such as chronic viral infection and cancer." (PMID 37122720, 2023). "At the moment of maximal cancer reduction, a decrease of Ki67 proliferative index, an increase of tumor CD8+ cytotoxic T cells, FoxP3+ Tregs, and NK cells, as well as an increase of granzyme B staining and IFN-gamma production, occur, confirming the increasing of cytotoxicity." (PMID 35628540, 2022). "Interestingly, granzyme B-mediated apoptosis is facilitated by interaction with SAMM50, suggesting a role for SAMM50 in cell death by reactive oxidative species and in lymphocyte-mediated cell death, e.g., of cancer cells." (PMID 36499681, 2022). "Importantly, the probe H5 does not fluoresce inside T cells, where GzmB is inactive, or in cancer cells when killed by other agents (i.e., staurosporine) that are not related to immune-mediated cancer cell death." (PMID 35501326, 2022). "The treated Pten-null;Cd8-KO prostates had almost no GZMb+ cells in the cancer areas." (PMID 35013322, 2022). "Therefore, SREBP inhibition may result in a reduction of NK cells growth, proliferation, and cytotoxicity against cancer cells by reduction of IFN-γ and granzyme B production." (PMID 33260925, 2020). "By estimating the cytotoxic T lymphocyte (CTL) activities through Perforin (encoded by PRF1) and Granzyme B (encoded by GZMB) expression, we observed a negative correlation between RGMB expression levels and CTL activities in 30 of 33 cancer types (p = 2.6 × 10−6, χ2 test)." (PMID 31061392, 2019). "The elevated level of Granzyme b in the CD8a+ T cells and the increased cellular killing seen by microscopy further indicates that the CTL effector mechanisms have been heightened in the presence of ILC2s, providing a mechanism for ILC2 action in anti-cancer immunity." (PMID 29440650, 2018). "This increase in specific cytotoxic activity was associated with a major increase in the cellular levels of the killing-mediator granzyme B. Our results suggest that this SIN may be used for generating T-cells with augmented cytotoxic function, for use in cancer immunotherapy." (PMID 29942308, 2018). "Moreover, the diverse CNV patterns in GZMB across the different cancer types, such as amplifications in TGCTs and deletions in UCS, are consistent with the notion that GZMB alterations may have distinct implications in different cancer contexts." (PMID 40002821, 2025). "Thus, an extensive analysis of GZMA, GZMB, GZMK and PRF1 may not only provide a greater understanding of their role in cancer biology, but also reveal their similarities and differences across different cancer types." (PMID 40002821, 2025). "In addition, the expression of granzyme B (GZMB) and genes involved in CD8+ TRM cell activation has been shown to be lower with EGFR-MT than the wild type, indicating that CD8+ TRM cells in EGFR-MT tumors have a lower anti-neoplastic activity to kill cancer cells." (PMID 36949948, 2023). "However, it is not clear how granzyme B and perforin granules enter into cancer cells." (PMID 38071322, 2023). "Cancer antigen–specific cytotoxic CD8+ T cells detect and lyse cancer cells by releasing cytolytic proteins, such as granzyme B.19We could not measure significant differences in effector cytokine levels (IFN‐γ, granzyme B) in T cells between responders and non‐responders (data not shown)." (PMID 33449393, 2021). "Notably, we observed a higher expression of GZMB and genes involved in T cell activation in TRM-like cells from EGFR-WT than in those from EGFR-MT, indicating that TRM-like cells in EGFR-WT tumors have the highest antitumor activity for the direct killing of cancer cells." (PMID 34663810, 2021).
cancer (continued). "In addition, our current understanding of the complete roles of GZMA, GZMB, GZMK and PRF1 are still evolving and other factors may play a role in the varying expression levels of these genes in the context of the different clinical prognoses seen in these cancer types." (PMID 40002821, 2025). "Again, this reactivity was not cancer-specific, with A4.TCR-T and C1.TCR-T producing IFN-γ and granzyme B in response to B cells and monocytes from MR1*04 heterozygous donors and not in response to MR1*01/02 donors." (PMID 39445059, 2024). "Regarding colon cell positivity for Granzyme-B, we found no positively stained cells in AAT-treated and non-treated control mice, whereas colon samples of AOM/DSS + AAT mice with cancer pT0 or pT1 stages were significantly more positive than samples of AOM/DSS mice." (PMID 37532996, 2023).